DNMT1 (DNA methyltransferase 1)
Diseases named in the same sentence as DNMT1 in open-access papers (continued):
Sharing a sentence is not in itself a finding about the gene and the disease.
myelodysplastic syndrome (107 papers, 2010 to 2025). A clonal hematopoietic disorder characterized by dysplasia and ineffective hematopoiesis in one or more of the hematopoietic cell lines. "While decitabine has proven effective for treating myelodysplastic syndromes, the novel DNMT1 inhibitor guadecitabine shows promise in targeting solid tumors and addressing some of the limitations faced by earlier inhibitors." (PMID 39996888, 2025). "DNMT1 inhibitors, already approved for treating myelodysplastic syndromes, warrant further clinical investigation for synovial sarcoma as repurposed, targeted treatments exploiting a vulnerability in the intrinsic biology of this cancer." (PMID 40299558, 2025). "In myelodysplastic syndrome, a recent report found significant responses to the combination of a DNMT1 inhibitor and a PDL1 inhibitor in some patients previously resistant to hypomethylating drugs." (PMID 38172923, 2024). "For the deoxycytidine analogue and DNMT1 inhibitor decitabine, clinically used in myelodysplastic syndrome (MDS) and AML, SAMHD1 expression also correlates with clinical outcome of patients receiving this therapy." (PMID 35583750, 2022). "To date, only two FDA-approved drugs (azacytidine and decitabine) are available that target DNMT1 in addition to other DNMTs for the treatment of myelodysplastic syndrome (Gnyszka, Jastrzębski, and Flis 2013)." (PMID 35898303, 2022). "Another DNMT1 inhibitor, decitabine, has antitumor effects in patients with myelodysplastic syndrome." (PMID 35008848, 2021). "The DNMT1 inhibitors azacitidine and decitabine are U.S. FDA-approved for treating acute myelomonocytic leukemia and myelodysplastic syndromes." (PMID 36432638, 2022). "Decitabine (DRUGBANK ID: DB01262) targets DNMT enzymes, specifically DNMT1, and is indicated for the treatment of patients with myelodysplastic syndromes." (PMID 34227253, 2021). "FDA-approved DNMT1 inhibitors, including decitabine and azacitidine, are currently used to treat myelodysplastic syndromes; however, these drugs target the enzymatic activity of DNMT1 rather than its interaction with NAA10." (PMID 40558489, 2025). "DNMT1 inhibitor, 5 Aza, an FDA-approved drug to treat myelodysplastic syndromes (MDS), can eradicate cancer stem cells of solid tumor by inducing cell apoptosis or differentiation." (PMID 30064482, 2018). "Until recently, DNMT proteins had not been found mutated in cancer, but DNMT3A, and later DNMT1 and DNMT3B, were reported as altered in patients with myelodysplastic syndromes and in acute monocytic leukemia, where their mutation status also predicted prognosis." (PMID 24063517, 2013). "Unlike DNMT1, somatic mutations in DNMT3A are prevalent in hematologic malignancies of myeloid and lymphoid lineage, including AML (~20%) and myelodysplastic syndromes (MDS; ~10%), and these mutations are associated with a poor prognosis." (PMID 36675240, 2023).
prostate carcinoma (99 papers, 2011 to 2025). A carcinoma that arises from epithelial cells of the prostate gland. "miR-152 normally targets oncogenic pathways (e.g., it can target DNA methyltransferase 1 and TGFα) and that its loss has been linked to increased proliferation, invasion, and therapy resistance in prostate cancer." (PMID 41462933, 2025). "Mechanistically, gDEC increases the mono- and di-methylation of H3K4 in prostate cancer cell lines and was associated with DNMT1 depletion." (PMID 37345101, 2023). "The multifaceted impact of DNMT1 across various signaling pathways and cellular mechanisms underlines its potential as a critical target in future prostate cancer treatments, particularly in strategies aimed at overcoming metastasis and resistance to conventional therapies." (PMID 40034825, 2025). "ChIPsequencing analyses showed in a prostate cancer cell model that the co-repressor DAXX (death domain associated protein) colocalized with DNMT1 near the TSS (transcriptional start site) of several ATG-related genes including ULK1 and DAPK3 (death-associated protein kinase 3)." (PMID 31861179, 2019). "TGF-β1 may increase DNMT1/3A expression and cause nuclear translocation of DNMT1/3A in prostate cancer and kidney fibrogenesis." (PMID 25544767, 2015). "Furthermore, overexpression of DNMT1 is a hallmark of endometrioid carcinomas and prostate cancer and it is also responsible for both de novo and maintenance methylation of tumor suppressor genes in various human cancer cells." (PMID 23613894, 2013). "In prostate cancer cells, for example, the cytosine-rich domain of antisense AR-eRNA, which is predicted to form a stem-loop structure, is key for AR-eRNA function, recruiting DNA methyltransferase 1 (DNMT1) to the associated enhancer to alter the DNA methylation levels of AR target loci." (PMID 36039999, 2022). "While DNMT1 remains a promising therapeutic strategy in prostate cancer, its clinical application faces a significant challenges and limitations." (PMID 40034825, 2025). "Isothiocyanates, including sulforaphane (SFN), modulate DNMT activity by downregulating DNMT1 and DNMT3a expression, particularly in breast and prostate cancer models." (PMID 40663150, 2025). "This was due to the fact that EGCG inhibits the catalytic site of DNMT1, and NaB can also decrease DNMT1 levels in breast and prostate cancer." (PMID 40004944, 2025). "More importantly, our study provides a novel RBM15/IGF2BPs/DNMT1 trans-omics regulation m6A axis, indicating the new crosstalk between RNA m6A methylation and DNA methylation in prostate cancer." (PMID 38658974, 2024). "miR-152 is present in prostate cancer and is involved in a feedback pathway with DNMT1, serving as a target gene for miR-152." (PMID 39606232, 2024). "The targeting of DNMT1 also resulted in an increase in histone methylation, drawing a functional link between DNMT1 and histone methyltransferases in prostate cancer." (PMID 37345101, 2023). "The promoter region of the E-cadherin gene is methylated in high-grade prostate tumors and cell lines, and treatment with the DNMT1-targeting decitabine restored E-cadherin mRNA expression in prostate cancer cell lines." (PMID 37345101, 2023). "Our findings demonstrate that 5-Aza-dC-mediated reprogramming and SPDEF expression enhancement can be replicated in aggressive prostate cancer cell lines by depleting DNMT1." (PMID 37900138, 2023). "DNMT1 knockdown upregulated H3K4me1 and H3K4me2, validating the effect of gDEC in the depletion of DNMT1 and upregulation of H3K4me1 and H3K4me2 in prostate cancer." (PMID 37345101, 2023).
prostate carcinoma (continued). "A recent, very promising study showed that the overexpression of DNMT1 and DNMT3B is highly linked to the genome-wide hypermethylation profile in prostate cancer and paved the way for studying their function in many malignances." (PMID 37894317, 2023). "Overall, these observations support the role of DNMT1-targeting with gDEC to reverse aberrant epigenetic repression of tumor suppressor programs and thereby treat prostate cancer." (PMID 37345101, 2023). "Molecular studies confirmed DNMT1 depletion and modulated epithelial-mesenchymal transition markers E-cadherin and β-catenin in several prostate cancer cell lines (LNCaP, 22Rv1, and MDA PCa 2b)." (PMID 37345101, 2023). "In this study, we determined the anti-prostate cancer effect of a small molecule drug guadecitabine (gDEC) that inhibits/depletes the DNA methylation writer DNA methyltransferase 1 (DNMT1)." (PMID 37345101, 2023). "MiR-185 and miR-152, act by suppressing DNMT1 activity in hepatocellular carcinoma cells and prostate cancer respectively, promoting PTEN expression, also shown to be associated with HMA resistance in MDS." (PMID 36555712, 2022). "Inhibition of GSK3 and the ensuing inhibition of DNMT1 activity resulted in re-expression of the Androgen Receptor (AR) and Estrogen Receptor (ER) in prostate cancer (PCa) and breast cancer (BCa) cells, respectively." (PMID 35402240, 2022). "Inhibition of the DNMT1 activity in prostate cancer-derived PC3 cells enhanced invasiveness and migratory capacity." (PMID 35578613, 2022). "In this study, the expression of FAM107A in DU 145 and PC 3 cell lines was restored to some extent by treating prostate cancer cells with the demethylating drug 5-Aza or by knocking down the expression of DNMT1 in siDNMT1 cells." (PMID 36010909, 2022). "In conclusion, these results suggest that hypermethylation of the FAM107A promoter region inhibited its expression in prostate cancer cells and that DNMT1 was involved in maintaining hypermethylation." (PMID 36010909, 2022). "On the other hand, DNMT1/3b-mediated DNA methylation also repressed the expression of multiple miRNAs in prostate cancer cells, thus forming a miRNA-DNMT1/3b feedback loop." (PMID 33589600, 2021). "Another studies has reported that downregulating HOTAIR degraded DNMT1 protein expression in prostate cancer cells and osteosarcoma cells." (PMID 33941772, 2021). "On the contrary, inhibition of CDKs with palbociclib in prostate cancer cells led to the decrease in DNMT1 levels and overall methylation and contributed to the reduction of the resistance to senescence." (PMID 31861179, 2019). "Then, we constructed recombinant plasmids consisting of the C‐terminal domains of both Dnmt1 and Dnmt3a methyltransferases fused to a zinc finger domain that specifically bind to PD‐L1 promoter of prostate cancer cell line DU145." (PMID 31090214, 2019). "An experiment with LNCap prostate cancer cells showed that SFN treatment reduced the expression of DNMT1 and 3b, resulting in a decrease in the global DNA methylation profile and cyclin D2 promoter methylation." (PMID 29977456, 2018). "In multiple human cell lines, such as bladder cancer and prostate cancer cells, levels of the DNMT1 and DNMT3β proteins are modulated by the PI3K/AKT/glycogen synthase kinase 3β (GSK3β) signaling pathway." (PMID 29467020, 2018). "Earlier studies in prostate cancer have analyzed various methyltransferases and found that DNMT1 expression was found to be lower than DNMT3b." (PMID 28235398, 2017). "To explore the mechanism of negative regulation of miR‐146a by PVT1, we analyzed the level of three active DNA methyltransferases (DNMT1, DNMT3a, and DNMT3b) in prostate cancer cell lines using qRT‐PCR when PVT1 was aberrantly expressed." (PMID 27794184, 2016). "In conclusion, DAXX binds active regulatory elements and co-localizes with DNMT1 in the prostate cancer genome." (PMID 26097870, 2015).
prostate carcinoma (continued). "The results of the prostate cancer model indicate that green tea inhibited mRNA and protein expression of DNMT1 in the tumour cells, which in turn reactivated antioxidative enzymes." (PMID 26161152, 2015). "Numerous reports have demonstrated the overexpression of DNMT1 in lung, hepatocellular, acute and chronic myelogenous leukemia, colorectal, gastric, breast and prostate cancers." (PMID 24001151, 2013). "Notably, miR-152-3p has been reported to be frequently downregulated in prostate cancer tissues, often via promoter hypermethylation, and to function as a tumor suppressor by restraining oncogenic signaling (e.g., the DNMT1-driven epigenetic circuit)." (PMID 41462933, 2025). "Prostate cancer may exhibit reduced aggressiveness upon termination of DNMT1 expression, as this leads to a corresponding decrease in Enhancer of Zeste Homologue (EZH2) expression." (PMID 40034825, 2025). "DNMT1 promotes prostate cancer progression and metastasis by enhancing TRAF6 transcription and facilitating TNF receptor-associated factor 6 (TRAF6)-mediated ubiquitination of EZH2, underscoring its pivotal role in tumorigenesis and potential as a therapeutic target." (PMID 40034825, 2025). "Consequently, IGF2BPs overexpression leads to increased overall R-loop levels, cell migration inhibition, and cell growth retardation in prostate cancer (PCa) via precluding the binding of DNA methyltransferase 1(DNMT1) to semaphorin 3 F (SEMA3F) promoters." (PMID 38658974, 2024). "They proposed that miR-152, which acts as a tumor suppressor, is inactivated by methylation, indicating that the epigenetic regulation of miR-152/DNMT1 may have a significant impact on the aggressiveness of prostate cancer." (PMID 39606232, 2024). "In addition, our research provides a novel RBM15/IGF2BPs/DNMT1 trans-omics regulation m6A axis, indicating the new crosstalk between RNA m6A methylation and DNA methylation in prostate cancer." (PMID 38658974, 2024). "Importantly, DNMT1-targeting with gDEC to reverse aberrant epigenetic repression of tumor suppressor programs suggests the therapeutic potential of treating prostate cancer." (PMID 37345101, 2023). "Furthermore, we confirmed that gDEC significantly decreased DNMT1 protein levels in prostate cancer cell lines in a dose- and time-dependent manner." (PMID 37345101, 2023). "Furthermore, we confirmed that H3K4me1 and H3K4me2 were impacted by DNMT1-depletion via gDEC, and we observed a consistent increase in H3K4me1 and H3K4me2 concurrent with growth inhibition in all three prostate cancer models evaluated." (PMID 37345101, 2023). "Our study suggested that one consequence of DNMT1 targeting by gDEC is the upregulation of KMTs, which could mediate the activation of tumor-suppressing programs and contribute to the overall prostate cancer phenotype change and anticancer effect." (PMID 37345101, 2023). "Similarly, the pretreatment of azacitidine and DNMT1 depletion sensitized metastatic castration-resistant prostate cancer cells to the cytotoxic chemotherapeutics cabazitaxel and docetaxel." (PMID 37345101, 2023). "Another DNMT1-inhibitor examined in prostate cancer cells, miRNA-342, is downregulated in AML." (PMID 36555712, 2022). "In addition, DNMT1 has been shown to physically interact with EZH2 to provide site-specific differential methylation in prostate cancer." (PMID 30089854, 2019). "Under the same experimental conditions, we found that 2i treatment did not cause a significant reduction of UHRF1 or DNMT1 proteins in LNCaP (prostate cancer), Bel7402, C33A and SiHa (cervical cancer) cells." (PMID 30696879, 2019). "In addition, PVT1 overexpression obviously increased the activity of DNA methyltransferases (DNMT1, DNMT3a, and DNMT3b) in prostate cancer cells." (PMID 27794184, 2016). "In conclusion, bound DAXX co-localizes with bound DNMT1 in the prostate cancer genome." (PMID 26097870, 2015).
prostate carcinoma (continued). "There are five members in the DNMT family, including DNMT1, DNMT2, DNMT3a, DNMT3b, and DNMT3L, the most common mutation of DNMT in cancer is the DNMT3a mutation, while DNMT3b is a pro-carcinogenic gene in endometrial, lung and prostate cancer, and a tumor suppressor gene (TSG) in lymphoma." (PMID 38200495, 2024). "Finally, independent of Gleason grade, increased DNMT1 expression was associated with biochemical recurrence following surgical treatment for prostate cancer." (PMID 21980391, 2011). "The co-expression of DNMT1 and the Enhancer of zeste homolog 2 (EZH2), alongside their correlation with poor prognostic markers in prostate cancer, underscores the importance of DNMT1 in maintaining tumor-promoting epigenetic landscapes." (PMID 40034825, 2025). "In prostate cancer models, DHA significantly downregulates expression of UHRF1 (Ubiquitin-like protein) and DNMT1." (PMID 40697663, 2025). "The data presented in this figure suggest that the expression of DNMT-1, PD1, Dicer1, and PD-L1 is markedly higher in prostate cancer patients compared to normal individuals and that their expression levels are positively correlated with the Gleason score." (PMID 40034825, 2025). "In vitro studies have shown that milk-derived miR-148 increased prostate cancer proliferation by inhibiting cyclin-dependent kinase inhibitor 1B (CDKN1B) and promoted DNA methyltransferase 1 (DNMT1)-dependent epithelial-mesenchymal transition (EMT)." (PMID 38201989, 2024). "For instance, curcumin treatment inhibited DNMT1 and DNMT3B expression in prostate cancer cells that resulted in promoter hypomethylation of miR-143 and miR-145." (PMID 38596245, 2023). "The positive feedback loop between DNMT1 and CAMK2N1 promotes the progression of prostate cancer in vivo and in vitro." (PMID 36755811, 2023). "We analyzed the expression of DNMT1, DNMT3A, DNMT3B, and the class I HDACs HDAC1, HDAC2, HDAC3, and HDAC8 in the PRAD and Taylor data sets and their correlation to HLA-I expression in prostate cancer." (PMID 36050516, 2022). "For example, DNMT1 induces histone demethylation of H3K9me3 and H3K27me3 on the promoters of Zeb2 and KLF4 in prostate cancer cells." (PMID 33616161, 2021). "HOTAIR contributes to Polyphyllin I-inhibited growth of castration-resistant prostate cancer cells by regulating DNMT1 and EZH2 in prostate cancer." (PMID 34405017, 2021). "In mouse TRAMP C1 prostate cancer cells, DIM reduced expression of both mRNA and protein for Dnmt1, Dnmt3a and Dnmt3b." (PMID 34660663, 2021). "The reduction of DNMT1 was previously shown to be correlated with induction of the epithelial–mesenchymal transition (EMT) and cancer stem cell (CSC) phenotype in prostate cancer cells." (PMID 33107222, 2021). "ALYREF, DNMT1, and TET2 were involved in the cell cycle, DNA replication, and prostate cancer-related pathways." (PMID 34325709, 2021). "Mahanine, a plant derived alkaloid, was shown to induce DNMT1 and DNMT3B proteasomal degradation by inactivating Akt, which in turn restored RASSF1A expression in prostate cancer cells." (PMID 33312959, 2020). "Disulfiram’s anticancer activity is mediated by its ability to suppress DNMT1 and through the reactivation of epigenetically silenced genes such as APC and RARB in prostate cancer cell lines (Section 1)." (PMID 33312959, 2020). "In support of this notion, a recent study showed that ERK kinase regulated DNA Methyltransferase 1 (DNMT1) and methylation of specific genes in prostate cancer cells." (PMID 27213343, 2016). "For example, in LnCaP prostate cancer cells (androgen–dependent) SFN significantly decreases expression of DNMT1 and DNMT3b on mRNA and protein level but the plant HDI has slight effect on DNMT1 protein level in PC3 and BPH-1 prostate cancer cells." (PMID 26703571, 2015).